MMP11 (matrix metallopeptidase 11)
Diseases named in the same sentence as MMP11 in open-access papers (continued):
Sharing a sentence is not in itself a finding about the gene and the disease.
tumor (continued). "The observation of MMP11 upregulation across cancer types is consistent with prior knowledge of gene function facilitating tumor invasion by degrading collagen, fibronectin, and laminin." (PMID 31200666, 2019). "The clinical significance of MMP-11 expression has been demonstrated previously by immunohistochemical studies on tumor specimens of OSCC patients." (PMID 28427180, 2017). "Previous studies suggested that miR-125a functioned as a tumor suppressor through targeting oncogenes such as MMP11 and IL-32Rα." (PMID 29043013, 2017). "Stromelysin-3 (MMP11 in mammals or Mmp11 in zebrafish) is over expressed in several cancers, where its abundance correlates with tumor aggressiveness and concomitant mortality rates." (PMID 27141287, 2016). "Five of these genes, CXCL12, MMP2, MMP11, VCAM1, and MME, which have previously been associated with tumor progression, angiogenesis, and metastasis, clearly discriminated between primary BC and BCBM." (PMID 27340107, 2016). "Proteases, e.g. cathepsin D, uPA, MMP-11, are secreted by transformed or stromal cells of BC, and impact on tumor invasion and mestastasis." (PMID 27538498, 2016). "In multivariate analysis lymphovascular invasion, CD147, MMP11 and tumor staging were independent prognostic factors related to overall survival (P = 0.044, 0.009, 0.028, <0.001, respectively)." (PMID 26507719, 2015). "Immunohistochemical staining showed a membranous and cytoplasmic staining of both CD147 and MMP-11 of tumor cells." (PMID 26507719, 2015). "Results showed that the mRNA levels of both CD147 and MMP-11 were much higher in tumor tissues than in normal tissues (P < 0.001, both)." (PMID 26507719, 2015). "Stromelysin-3 or MMP-11 is implicated in extracellular matrix remodeling, increased tumor uptake along with anti apoptotic and anti necrotic effect during cancer progression." (PMID 25888629, 2015). "Although MMP-11 can’t degrade any ECM component, it is also associated with tumor progression and poor prognosis." (PMID 25887589, 2015). "As expected from previous data 6, peritumoral fibroblasts and cancer-associated adipocytes (CAAs) that are adipocytes located at the cancer cell contact 31, expressed MMP-11 at the tumor invasive front." (PMID 25081520, 2014). "Our findings validate MMP11 as a potential biomarker for these tumor types and a suitable target for cancer immunotherapy strategies." (PMID 24564996, 2014). "Although these data can serve as references for the application of MMP-11 as a tumor marker, the specimens in these studies were obtained from surgical tumors or biopsied samples." (PMID 25423087, 2014). "The levels of MMP-11 were significantly higher in patients with advanced tumor extent (T2: 16.10±9.74 ng/mL, T3: 18.58±10.82 ng/mL and T4: 17.16±10.39 ng/mL) when compared with T1 (11.48±6.56 ng/mL) patients." (PMID 25423087, 2014). "The clinicopathological significance of MMP-11 has also been demonstrated by immunohistochemical staining on tumor specimens of OSCC patients." (PMID 25423087, 2014). "In these groups we analyzed by real-time PCR the differential expression of 65 factors related with tumor progression and inflammation and found differences in the RNA expression of 26 factors, that were therefore related with MMP-11 expression by MICs." (PMID 23145063, 2012). "Such anti-tumor effects or dual functions with protective roles in specific circumstances have been extended to other proteinases including MMP11, MMP12, MMP19, MMP26." (PMID 22822400, 2012). "The classification of these tumor groups in good or bad prognosis was based on the expression of MMP-11 by MICs by our group." (PMID 23145063, 2012). "Nevertheless, the most relevant finding was the association between high CD68/(CD3+CD20) ratio and the expression of MMP-11 (stromalysin-3) or TIMP-2 by the MICs at the tumor center." (PMID 23300781, 2012).
tumor (continued). "These factors showing an increased expression level in tumors infiltrated by MMP-11 positive MICs, like IL-1, −5, −6, −17, IFNβ and NFκB, have a great biological interest because of their relation with tumor progression." (PMID 23145063, 2012). "Despite the pro-tumorigenic function of certain metalloproteinases, recent studies have shown that other members of these families, such as MMP8 or MMP11, have a protective role against tumor growth and metastasis in animal models." (PMID 22822400, 2012). "We also found that Snail overexpression induced increased expression of VEGF and MMP11, which are known markers of tumor invasion and metastasis." (PMID 23151184, 2012). "The classification of these tumor populations in good or bad prognosis was based on the expression of MMP11 by MICs by our group." (PMID 23145063, 2012). "Several other authors have confirmed the tumor growth suppression effect of let-7 family members, among them let-7c, which influences MMP11 and PBX3 gene expression." (PMID 23091478, 2012). "Let-7c was confirmed to have a tumor growth suppressor role but also found to be a tumor metastasis suppressor, which directly destabilizes the mRNA of MMP11 and PBX3 oncogenes." (PMID 23091478, 2012). "The most differentially expressed factors were then analyzed in a wider tumor population classified according to MMP-11 expression by MICs and also according to metastasis development." (PMID 23145063, 2012). "Thereafter, we confirmed in the wider tumor population, that there is a higher expression of those factors in tumors infiltrated by MMP-11 positive MICs." (PMID 23145063, 2012). "MiR-98 binding sites were identified in various mRNAs, many of which were associated with tumor growth and invasion including Activin A receptor, type IB or ALK4, and Matrix metalloproteinase-11 or MMP11." (PMID 23211491, 2012). "Clinicopathological studies have demonstrated that MMP-11 is an important factor in tumor progression in various malignant tumors including pulmonary cancer, head and neck carcinoma and breast carcinoma." (PMID 21513571, 2011). "Patients with tumours showing MMP-11 or -13 score values greater than median had a significant higher probability of biochemical recurrence than those patients with lower MMP-11 or -13 score values (P=0.02 and P=0.001, respectively) (respectively)." (PMID 20160732, 2010). "Opposing effects on local tumor growth and systemic tumor burden have historically been reported for stromelysin-3 (MMP11)." (PMID 21170377, 2010). "The cytoplasm of tumor cells expressed a high amount of MMP-11 with several adjacent stromal cells being positive, too." (PMID 19531263, 2009). "MMP11 has recently been shown to exhibit protease activity towards type VI collagen and to promote tumor progression." (PMID 19187537, 2009). "Overexpression of specific MMPs, as the gelatinases A (MMP-2) and B (MMP-9) and stromelysin-3 (MMP-11), have been widely associated to tumour progression and metastasis in different tumours." (PMID 19753302, 2009). "Positive immunoreaction was detected in the cytoplasm of cervix epithelium tumor cells, differing from other tumor tissues, where MMP11 expression is restricted to stromal cells that surround the neoplastic area." (PMID 15989693, 2005). "Moreover, infiltration of natural killer (NK), mast, and NK CD56 bright cells was enhanced in tumor tissues with high MMP11 and MMP17 expression." (PMID 41228294, 2025). "Given the progressive increase in MMP11+ mCAFs with tumor development, we hypothesize that this population may revert along these pathways." (PMID 40552583, 2025). "Since only a small fraction of F01 cells expressed MMP11, we hypothesized that MMP11(+) fibroblasts specifically drive tumor progression." (PMID 40607407, 2025). "Notably, in the later stages of tumor progression, the poor‐prognosis MMP11+ mCAFs predominate, whereas IGLC1+ CAFs are more prevalent in the early stages." (PMID 40552583, 2025).
tumor (continued). "Furthermore, interferon‐associated basal‐like tumor cells secrete BMP2, which induces the expression and activity of NFE2L3, a transcription factor specific to MMP11+ mCAFs, promoting WNT5A expression." (PMID 40552583, 2025). "Furthermore, analysis of the MMP11 expression in the broad panel of tumor samples and normal tissues using the GEPIA 2 web tool suggested that in addition to PCa, it is overexpressed in almost all types of cancer." (PMID 40122809, 2025). "In addition, we demonstrated that the ITGA11+ myCAF subgroup produced a cascade signalling under TGF‐β/TGFR activation and highly expresses ECM‐related genes such as COL11A1 and MMP11, assisting tumor cells in initiating the metastatic program." (PMID 41017455, 2025). "We analyzed the relationship between MMP11 and MYL9 gene expression and tumor mutational burden." (PMID 41009818, 2025). "Furthermore, spatial transcriptomics on human PDAC tissue revealed that iCAFs using gene markers IL6 and CXCL12 and myCAFs using gene markers ACTA2 and MMP11 were spatially distributed and correlate with tumor and immune cell localizations." (PMID 41376815, 2025). "Comparison of the average expression of a selected panel of genes across samples revealed that Gpnmb and Mmp11 were co-upregulated in tumor cells from the most mesenchymal-like (M) clone, further supporting the association of these genes with a mesenchymal-like phenotype." (PMID 41280107, 2025). "Furthermore, matrix metalloproteinase 11 (MMP11) derived from macrophages promotes the migration of HER2+ tumor cells through the CCL2–CCR2 axis." (PMID 40092996, 2025). "Noteworthy, we further proved that MMP11 significantly promoted PCa probably through reprogramming of tumor microenvironment, which might provide a promising-target for PCa treatment." (PMID 40607407, 2025). "Emerging studies highlight MMP11’s regulatory role in the tumor microenvironment (TME), which may contribute to PCa progression." (PMID 40607407, 2025). "Interestingly, exosomes secreted by activated fibroblasts contain the miRNA-139, which is negatively correlated with MMP11 and can inhibit tumor progression by suppressing MMP11." (PMID 40309240, 2025). "Collectively, these findings suggest that MMP11+ mCAFs may play a key role in promoting tumor angiogenesis." (PMID 40552583, 2025). "TCGA tumor samples were divided into two groups according to the median expression of MMP11." (PMID 39239548, 2024). "In addition, increased MMP-11 expression was correlated with the pathologic tumor stage, lymph nodes metastasis, vascular and perineural invasion." (PMID 39272712, 2024). "While the treatment with TGF-β1 neutralizing antibodies could suppress the expression levels of FAP and MMP11 in fibroblasts when co-cultured with UPP1-overexpressing tumor." (PMID 38331898, 2024). "Additionally, immunohistochemical analysis of CRC samples and adjacent normal tissues confirmed that MMP11 was highly expressed in tumor tissues." (PMID 39239548, 2024). "Additionally, MMP-11 function on stromal adipocytes near the tumor invasion front suggests a direct contribution to invasion." (PMID 38438841, 2024). "MMP11 was highly expressed in the cancerous ductal epithelium and might act as a tumor promoter in PDAC, stimulating cyclin-dependent kinase 4 and cyclin D1." (PMID 38572434, 2024). "Our findings suggested that MMP11 was positively correlated with macrophages M0 and negatively related to macrophages M1, NK cells activated, NK cells resting, T cells CD4 memory activated, and T cells follicular helper, indicating the remarkable interactions between MMP11 and tumor immunology." (PMID 39239548, 2024). "Most importantly, MMP11 was positively associated with M0-macrophages and negatively associated with M1-macrophages, NK cells activated, NK cells resting, T cells CD4 memory activated, and T cells follicular helper, indicating the remarkable interactions of MMP11 with tumor immunology." (PMID 39239548, 2024).
tumor (continued). "Intriguingly, several studies also reported MMP-11 expression within tumor cells themselves." (PMID 38438841, 2024). "They support the notion that MMP-11 is specifically expressed in the tumor microenvironment." (PMID 38438841, 2024). "In addition, their analysis showed that the upregulation of MMP11, MMP14, MMP17, and MMP19 is significantly associated with a more advanced tumor stage and a worse long-term prognosis." (PMID 37511338, 2023). "We discovered that in LUAD, MMP11 expression was higher in tumor tissues than in normal tissues." (PMID 36756152, 2023). "Using the MMP11 antibody led to a considerable reduction of tumor growth in a xenograft model." (PMID 36756152, 2023). "The clinical samples we collected were all primary untyped treated sample tissues, so the low level of CD8+PD1+ T cells infiltration in the tumor parenchyma of the MMP11 positive expression group may suggest poor efficacy of ICIs." (PMID 36756152, 2023). "Moreover, HK2, MMP11, CDH3, PDK4, SERPINB5, and SLC2A1 expression were closely associated with tumour stages." (PMID 37234801, 2023). "Although, compared with other MMPs, MMP11 has relatively low proteolytic potential and there are other mechanisms which could explain the special relevance of MMP11 in tumor progression." (PMID 35885510, 2022). "Previous studies have suggested that the MMP-11 may play a regulatory role in cancer cell growth, tumor migration, invasion, and metastasis in various cancers." (PMID 35885589, 2022). "Moreover, MMP-11 levels were also correlated with late stage, larger tumor sizes, and lymph node metastasis." (PMID 35885589, 2022). "MMP-1, MMP-2, MMP-8, MMP-11, and MMP-13 are implicated in the regulation of tumor cell migration." (PMID 36776395, 2022). "Of note, analyses of TCGA revealed that MMP-11 levels were correlated with larger tumor sizes." (PMID 35885589, 2022). "In addition, this same study found that these adipocytes at the tumor invasive front that expressed MMP-11 were reduced in size." (PMID 36551185, 2022). "On the other hand, there is evidence that MMP11 may alter the stromal microenvironment of human carcinomas to stimulate tumor angiogenesis." (PMID 35885510, 2022). "Moreover, MMP-11 can participate in the increased survival of BCC tumor cells even when NK cells release cytotoxic molecules." (PMID 35572966, 2022). "Also, our data proved that the expression levels of circ-MMP11 and ANLN were significantly decreased in tumor tissues derived from the sh-circ-MMP11 groups relative to the sh-NC groups, while miR-153-3p expression presented an opposite trend in this xenograft." (PMID 34295807, 2021). "Also, in the clinicopathological and prognosis analyses, upregulated MMP11, MMP14, MMP17, and MMP19 were significantly associated with a higher tumor stage and a worse prognosis." (PMID 34804973, 2021). "Interestingly, we found that combined sh-circ-MMP11 and lapatinib showed a more distinct suppression on tumor growth." (PMID 34295807, 2021). "To assess the impact of MMP11 on tumor development, we measured palpable tumor sizes with a caliper in individual mammary glands of PyMTTg; MMP11Tg and PyMTTg; MMP11KO mice and compared them with their respective controls because both lines are on a different genetic background (Figure S1Bb’,Bb)." (PMID 32825455, 2020). "In the light of the physiological role of MMP11, we hypothesized that MMP11 stimulates lipid utilization and promotes aerobic glycolysis, a process known as the Warburg effect, to support tumor growth." (PMID 32825455, 2020). "In the PyMT model, MMP11 influences tumor growth and metabolism, whether its catalytic activity is required for these functions remains uncertain." (PMID 32825455, 2020). "Matrix metalloproteinase-11 (MMP-11) has an important role in tumor migration and metastasis." (PMID 33369474, 2020).
tumor (continued). "It is important to highlight this dual effect because MMP-11 could function as a significant tumor biomarker in cancer for tumor staging, prognostic analysis, monitoring of recurrence during follow-up, for immunotherapy, and for early detection." (PMID 33419373, 2020). "Besides lactate utilization, in the presence of MMP11 lipid turnover is increased (e.g., synthesis, transport, and metabolism) to serve as an additional nutrient source to fulfill tumor energetic needs allowing new membrane formation and expansion." (PMID 32825455, 2020). "MMP-11 is highly expressed in colonic carcinoma, as well as in several neoplasms." (PMID 32813775, 2020). "Both models were consistent and showed that MMP11 favors tumor growth at an early stage." (PMID 32825455, 2020). "Moreover, this study brings novel insight into the metabolic role of MMP11 in tumor growth through induction of metabolic reprogramming." (PMID 32825455, 2020). "Andrographolide decreased tumor volume, MMP11 expression and blood vessels formation in vivo." (PMID 30800220, 2019). "Our results show that Andrographolide decreases the expression of MMP11 in tumor tissue." (PMID 30800220, 2019). "MMP-11 can be a crucial tumor biomarker and a potential target for immunotherapy." (PMID 29983921, 2018). "The MMP-11 (stromelysin-3) seems facilitating tumor development through apoptosis inhibition." (PMID 29983921, 2018). "MMP11 is related to invasion and migration, two mechanisms strictly connected to tumor growth." (PMID 30622662, 2018). "In parallel, MMP-11 can directly act on adipocytes and negatively regulate adipogenesis by inhibiting adipocyte differentiation and by enhancing dedifferentiation, leading to accumulation of fibroblast-like cells in the tumor microenvironment." (PMID 28915700, 2017). "Importantly, cancer cells were shown to induce the expression of MMP-11 in adipocytes as tumor invaded the surrounding adipose tissue." (PMID 28915700, 2017). "In our experiment it could be hypothesized that increased expression of MMP-11 and Collagen I found after co-culture, may impact cancer microenvironment, to explain the tumor-promoting effect of dedifferentiated cells observed in other experimental settings." (PMID 26958939, 2016). "This Warburg-like effect observed in adipose tissues might provide a rationale for the deleterious impact of CAA-secreted MMP11, favouring tumor progression." (PMID 27126782, 2016). "Despite the established pro‐tumorigenic roles of certain MMPs (e.g., MMP2, MMP9, and MT1‐MMP), recent studies have demonstrated that some MMPs such as MMP8 and MMP11 might act against tumor growth and metastasis." (PMID 27292876, 2016). "The mechanism by which MMP-11 participates in tumor progression is also unique." (PMID 26507719, 2015). "MMP11 thus differs from other MMPs that are expressed as proenzymes and processed to active forms through proteolytic cleavage activated extracellularly, indicating that MMP11 may have a unique role in tumor development and progression." (PMID 24564996, 2014). "Two of them, ADAM15 and MMP11, were known to play important roles in tumor invasion." (PMID 23211491, 2012). "Moreover, the total RNA and protein of each representative tumor from mice were used for analyses of the expression levels of miR-125a, MMP11 and VEGF-A target genes by qRT-PCR and western blot." (PMID 22768249, 2012).